BCL2 (BCL2 apoptosis regulator)
Diseases named in the same sentence as BCL2 in open-access papers (continued):
Sharing a sentence is not in itself a finding about the gene and the disease.
lymphoma (continued). "The upregulation of Gas6, Mrc1, Cd36 and Timp2 expression by M(IFN-γ/LPS) macrophages was specific for coculture with apoptotic cells, as coculture with unstimulated or Bcl-2-transfected lymphoma cells did not lead to a significant upregulation of these genes." (PMID 28157210, 2017). "The expression of c-MYC and BCL2 in the “double-expressor” lymphomas is independent of c-MYC or BCL2 gene rearrangement, and is only used as a prognostic marker rather than diagnostic criteria." (PMID 28379189, 2017). "Thus, BCL2 and MYC rearrangements affect the disease prognosis differently in accordance to the histological subtypes of lymphoma." (PMID 28086220, 2017). "DLBCLs with co-expression of c-MYC and BCL2 are termed “double-expressor lymphomas” and most do not have concurrent c-MYC and BCL2 gene rearrangements." (PMID 28379189, 2017). "Follicular colonization was noted in the lymphomas without a BCL2 rearrangement, which was strongly overlapping with the morphological features of NMZL." (PMID 27398102, 2016). "However BCL6 also directly represses several DLBCL oncogenes such as BCL2 and BCL-XL that promote lymphoma survival." (PMID 26657288, 2016). "Since BCL-2 is known to prevent apoptosis, we investigated whether PNT2258 treatment induced apoptosis in these cells and in two other lymphoma cell lines with different BCL-2 expression characteristics." (PMID 27283896, 2016). "However, BCL6 inhibition also activates BCL6 target genes such as BCL2 and BCL2L1 (BCL-XL), and secondary MCL1, which can sustain lymphoma survival by suppressing the activity of pro-apoptotic BH3 proteins." (PMID 26657288, 2016). "Notably, DHLs or triple-hit lymphomas are classified in the new category of ‘high-grade B-cell lymphoma (HGBL), with rearrangements of MYC and BCL2 and/or BCL6’ in the 2016 updated WHO classification." (PMID 27606052, 2016). "The cases presented herein, despite the absence of the IGH-BCL2 translocation and the corresponding BCL2 protein overexpression, demonstrate aberrant morphologic and immunophenotypic features that are typical of lymphoma." (PMID 26991267, 2016). "Lymphoma cells in all cases showed diffuse expression of the Myc protein, while Bcl2 was dim or negative; moreover, the strong expression of phosphorylated-STAT3 in tumor cell nuclei suggested activation of the JAK-STAT pathway." (PMID 27398102, 2016). "Raji-4RH and RL-4RH lymphomas do not express Bcl-2 and, for this reason, ABT-263 treatment resulted inefficacious, either as a single agent or in combination, even at high micromolar doses." (PMID 26658189, 2015). "While the example of BCL-2 translocation in lymphoma is not observed in many tumor types, over-expression of anti-apoptotic members of the BCL-2 family is a common feature in cancers of the uterus, lung, ovary, breast, colon, liver, and gastrointestinal tract." (PMID 25621172, 2014). "Morphologically double hit lymphomas can have the appearance of BL, DLBCL, or follicular lymphoma whilst immunohistochemical studies suggest that the majority coexpress CD10, BCL6, and BCL2 and have a proliferation index between 50 and 100% as assessed by Ki67 staining." (PMID 25349747, 2014). "BCL-2 levels showed a negative correlation with p62 in FL (P<0.05) and positive correlation with p62, LC3 or Beclin-1 in DLBCL (P<0.01), suggesting that BCL-2 does not play a dominant role in autophagy status in these lymphomas." (PMID 25362242, 2014). "Our study also suggested that the combined treatment of Bcl-2 siRNA and miR-15a mimics plus MTX could be potentially used as a novel therapy for human lymphomas." (PMID 23691440, 2013). "Bcl-2 siRNA and miR-15a combined with MTX may be a useful approach to improve the treatment effects on lymphoma." (PMID 23691440, 2013).
lymphoma (continued). "Although there is one paper describing an interaction between GR and Bcl-2 in the mitochondria, GC-induced mitochondrial GR translocation in GC-sensitive thymocytes and lymphoma cells proceeded in the absence of Bcl-2." (PMID 23431463, 2013). "Other lymphomas, such as those involving the skin and testis, are typically negative for bcl-2 protein and have no bcl-2 gene rearrangement when this has been evaluated." (PMID 22257663, 2012). "Cytogenetic characterization of these BCLu has shown that a proportion of them harbours a complex karyotype with two main genetic events—usually cMYC alterations together with BCL2 and/or BCL6, less commonly CCND1 rearrangements, designated the so-called “double hit” lymphomas (DHL)." (PMID 22548066, 2012). "The lymphoma cells of all eight MALT lymphoma cases were positive for Bcl2 and negative for CD5, CD23, CD10, Bcl6, MUM1, and CD25." (PMID 22395482, 2012). "These lymphomas carry either IG-MYC fusion or non-IG-MYC fusion in combination with either BCL2 and/or BCL6 breaks." (PMID 22548066, 2012). "We used FISH to screen for BCL2 rearrangements in all of our lymphoma cases that were not previously tested for this aberration." (PMID 22194861, 2011). "We found these mutations to occur more frequently in BCL2-rearranged lymphomas than in lymphomas lacking a BCL2 rearrangement." (PMID 22194861, 2011). "On the other hand, a recent report from the French group shows benefit in both Bcl-2-positive and Bcl-2-negative lymphomas using the method of competing risks." (PMID 21437222, 2010). "Therefore, an antitumor potential of bcl-2 siRNA and cyclophosphamide was examined ex vivo using the RLS lymphosarcoma." (PMID 20470373, 2010). "Our results are consistent with a recent study demonstrating that Bcl-2 is not strictly required for the development of myc induced lymphomas in Eu-myc transgenic mice." (PMID 19209227, 2009). "We do not believe that an inherent feature of Eμ-Myc lymphomas make them particularly sensitive to the effects of elongation inhibitor/Dxr combination since Eμ-Myc/Bcl-2 lymphomas showed significant resistance to these drug combinations." (PMID 19412536, 2009). "Finally, other investigators have recently shown that Bcl-2 antagonists like gossypol, can increase bortezomib-mediated cellular stress and SAPK/JNK activation in lymphoma cells." (PMID 19852810, 2009). "This behaviour is consistent with the agent’s ability to inhibit colony formation of Eμ–myc lymphoma cell lines overexpressing Bcl-2, but not Mcl-1 or A124." (PMID 19079626, 2008). "In contrast to the result with Bcl-2, the absence of p27 had no impact on lymphoma formation in mice expressing pro-apoptotic Bax." (PMID 18382684, 2008). "Previous studies found that lymphoma formation is observed in Lck-Bcl-2 transgenic mice but significant penetrance is not observed until after 1 year of age." (PMID 18382684, 2008). "However, previous studies have shown that both compounds specifically degrade Bcl-xL but not Bcl-2 in lymphoblast cell lines and lymphomas." (PMID 40141414, 2025). "This indicated that BCL-2 and c-MYC may synergize to transform B lymphoid cells, but he held a lingering worry that if the Eμ-Myc transgenic mice that provided the bone marrow had a pre-clinical lymphoma, the results might have been skewed." (PMID 40204952, 2025). "Immunohistochemical analysis showed strong diffuse positivity for CD99, alongside vimentin, BCL2, Cyclin D1, and C-Kit expression, while markers such as CK7, CK20, S100, and CD34 were negative, effectively ruling out differential diagnoses such as rhabdomyosarcoma, lymphoma, and other SRCTs." (PMID 41466962, 2025).
lymphoma (continued). "Other tumor biomarkers are today commonly evaluated, including CD20, Ki-67, as well as MYC, BCL2, and BCL6, since a worst prognosis is predicted by the co-occurrence of MYC rearrangements with BCL2 and/or BCL6 rearrangements (i.e., “double-hit” and “triple-hit” lymphoma, respectively)." (PMID 38835350, 2024). "In addition, new analysis predicted lymphoma subtypes using cell-of-origin markers that hematopathologists use in the clinical routine, including CD3, CD5, CD19, CD79A, MS4A1 (CD20), MME (CD10), BCL6, IRF4 (MUM-1), BCL2, SOX11, MNDA, and FCRL4 (IRTA1)." (PMID 38745770, 2024). "From a practical standpoint, HGBCL, nos are a diagnosis of exclusion in which a lymphoma with intermediate or blastoid cytomorphology and starry sky pattern triggers a “high grade” workup to exclude BL, HG/LBCL-11q, and HGBCL with MYC- and BCL2- and/or BCL6-rearrangement." (PMID 37530792, 2024). "Despite the prototypical phenotypic and molecular-genetic findings, other types of FL have been recognized, including lymphoma BCL-2-rearranged-negative (BCL2-R-negative), CD23-positive follicular center lymphoma, pediatric-type FL and primary cutaneous centro-follicular lymphoma." (PMID 39682103, 2024). "Most studies agree in recognizing that patients with DH lymphoma have lower survival than other DLBCL, while results are still controversial on the prognostic role of the isolated MYC translocation or immunohistochemical overexpression alone of MYC, BCL2, and/or BCL6 (DE lymphomas)." (PMID 38534887, 2024). "In patients with double expressing lymphomas, where co-expression of MYC with BCL2 on immunohistochemistry are detected without associated translocations identified on in-situ hybridization, CNS recurrence risks can be as high as nine percent as compared to two percent in non-expressors." (PMID 38173015, 2024). "High-grade B-cell lymphoma with MYC and BCL2 and/or BCL6–R (DHL/THL) are defined by their genetic background and were recognized as highly aggressive B-cell lymphomas that can occur de novo or as transformations from prior lymphomas, most often FL or DLBCL, nos." (PMID 37530792, 2024). "Other typical lymphoma translocations, such as BCL2 and BCL6, do not occur in this entity." (PMID 37672206, 2024). "The absence of BCL-2 also did not delay lymphoma development, and this is explained by the observation that its levels are very low in pre-B and immature B lymphocytes, the cells from which these lymphomas arise." (PMID 37567974, 2023). "Here we hypothesized that adaptive mechanisms to MYC-induced replicative and oxidative stress, consisting in DNA damage response (DDR) activation and BCL-2 overexpression, could represent the biologic basis of the poor prognosis and chemoresistance observed in MYC/BCL-2-positive lymphoma." (PMID 34304248, 2022). "Besides double-hit (DH) or triple-hit (TH) lymphomas, referring to translocations involving the MYC and BCL2 and/or BCL6 genes detected via FISH, the double-expressor (DE, assessed by IHC) lymphoma phenotype refers to strongly detectable protein expression of the MYC and BCL2 gene products." (PMID 35326604, 2022). "Moreover, IACS‐010759 synergized not only with venetoclax to kill MYC/BCL2 DHL tumor cells in vivo and in vitro, as previously shown with tigecycline, but also with the MCL1 inhibitor S63845 against BCL2‐negative lymphoma cell lines." (PMID 36214609, 2022). "Currently, HGBL is subgrouped as HGBL with MYC and Bcl-2 and/or Bcl-6 rearrangements, so-called double- or triple-hit lymphoma (HGBL-DH or HGBL-TH, respectively) and as HGBL, not otherwise specified (HGBL-NOS), which lacks MYC and Bcl-2 and/or Bcl-6 rearrangements." (PMID 35686130, 2022). "In this case study, the lymphoma cells exhibited high levels of BCL2A1 expression and it was suggested that BFL-1 could play a role in the survival of these cancer cells similar to the role played by BCL-2 in the more common MYC/BCL-2 double-hit lymphomas." (PMID 35900226, 2022).
lymphoma (continued). "The lack of venetoclax responses in BCL2-negative DLBCL supports the notion that the presence of BCL2 protein is required to obtain a response to venetoclax, and that patients who have BCL2-negative lymphomas may not benefit from venetoclax-based regimens." (PMID 33670870, 2021). "On immunohistochemistry of the lymph node biopsy, Bcl2 was negative, excluding lymphoma." (PMID 34176492, 2021). "In summary, the BH3 profiling of primary NHLs shown here supports at least three causes of poor venetoclax responses: pro-apoptotic signaling defects, a lack of BCL2 protein expression in high-grade lymphomas, as well as co-dependence on MCL1, observed in all NHL subtypes." (PMID 33670870, 2021). "Differently from tumors with an immunohistochemical expression of MYC and BCL2 (double expressors), aggressive B-NHLs harboring MYC and BCL2 or MYC and BCL6 rearrangements—when identified with FISH—present an even more aggressive behavior, and are also referred to as double-hit lymphoma." (PMID 34943410, 2021). "The pro-survival BCL-2 proteins: B-cell leukemia/lymphoma-2 (BCL-2/BCL2), myeloid cell leukemia-1 (MCL-1/MCL1) and B-cell lymphoma-extra large (BCL-XL/BCL2L1) are frequently (over)expressed in B-NHL, which plays a crucial role in lymphoma pathogenesis, disease progression, and drug resistance." (PMID 32290241, 2020). "Not all lymphoma subtypes, however, rely on BCL2 antiapoptotic signaling for survival." (PMID 32197371, 2020). "Lymphomas that carry MYC and either a BCL2 or a BCL6 translocation (a double-hit lymphoma, DHL) or all three rearrangements (a triple-hit lymphoma, THL) are included in the current WHO classification as a new entity termed “High-grade B cell lymphomas with MYC and BCL2 and BCL6 rearrangements”." (PMID 32102485, 2020). "Among the participants given R-CHOP (including the non-randomised group), MYC rearrangement, double-hit lymphoma, and dual high MYC and BCL-2 mRNA expression were significantly associated with inferior progression-free survival after controlling for IPI (data not shown)." (PMID 30948276, 2019). "In addition, patients with MYC and BCL2 protein co-expression who did not harbour genetic alterations were defined as having “double-expressor” lymphoma (DEL), which accounted for approximately 19–34% of cases of DLBCL." (PMID 31315646, 2019). "Bcl-2 inhibitors may be another option for CD20 negative lymphomas and warrant further investigations." (PMID 28191314, 2017). "Thus, miR21-mediated p-STAT3 phosphorylation was necessary for the induction of ICOS expression on Treg cells, independent of Bcl-2 expression of lymphoma cells." (PMID 28637496, 2017). "Therefore, irrespective of lymphoma cell Bcl-2 status, miR21 sensitized B-lymphoma cells to ABT-199 in the presence of tumor microenvironment." (PMID 28637496, 2017). "Indeed, we found that both Bcl-2 inhibitor venetoclax, and SMAC-mimetic LCL-161 sensitized OCI-LY3 cells to FasL, suggesting that those represent viable potential combination strategies in lymphoma." (PMID 28177892, 2017). "In this study, we set out to substantiate the hypothesis that a subset of lymphomas that are initially classified as FL without BCL2 translocation (translocation-negative FL), actually represent NMZL." (PMID 26949422, 2016). "The BCL2-selective BH3 mimetic venetoclax was recently approved for the treatment of relapsed, chromosome 17p-deleted chronic lymphocytic leukemia (CLL) and is undergoing extensive testing, alone and in combination, in lymphomas, acute leukemias, and solid tumors." (PMID 27990281, 2016). "The presence of overexpression of Bcl-2 in other lymphoma types is not well documented." (PMID 26482649, 2015).
lymphoma (continued). "In order to improve cytopathological diagnostics in lymphoproliferative disorders with inconclusive sIg LC in the absence of specific lymphoma immunophenotype cytoplasmic immunoglobulin (cIg) LCs or Bcl-2 could be helpful." (PMID 26482649, 2015). "However, other lymphomas with MYC and BCL2 rearrangements have received less attention." (PMID 26517511, 2015). "Pearson correlation coefficient for expression analysis of the Lymphoma/Leukemia Molecular Profiling Project (LLMPP) demonstrated Aurora A and B are highly correlated with MYC in DLBCL and mantle cell lymphoma (MCL), while both Auroras correlate with BCL2 only in DLBCL." (PMID 24893165, 2014). "After determining that the expression of Bcl-2 in the AKR/J spontaneous lymphomas was not altered while Fas expression was markedly decreased in all thymomas tested, the mechanisms underlying apoptosis induced by bacterial Sags in two lymphomas were studied." (PMID 21203530, 2010). "By 28 hrs post-drug delivery, there was a reduction in the amount of Mcl-1, Cyclin D1, and c-Myc protein levels in Pten+/−Eμ-Myc lymphomas relative to vehicle-treated controls (compare lanes 2–6 to 1) whereas the levels of β-actin or Bcl-2 did not appreciably change over this time period." (PMID 19412536, 2009). "However, the Thai Lymphoma Guideline 2022, mentions that in cases where the FISH technique cannot be used, IHC detects MYC and BCL2 expression, referred to as double expression (DE), which may correlate with a poorer prognosis than those without or with single expression." (PMID 39038016, 2024). "Additionally, BCL2 amplicon loss was detected in the HBL-2 mantle cell lymphoma line and the VAL double-hit/HGBL lymphoma line, although this is unlikely to be a major venetoclax resistance mechanism in DLBCL since BCL2 amplification in DLBCL occurs infrequently." (PMID 38893249, 2024). "Similarly, the Eμ-BCL2 transgenic strain, which places human BCL2 under the control of the 5’ IGH enhancer Eμ, shows an expansion of B cells and plasma cells, associated with autoimmune kidney disease but without increased incidence of lymphoma." (PMID 38022603, 2023). "In addition to COO, chromosomal translocations of BCL6, BCL2, and c-MYC are common cytogenetic abnormalities in DLBCL, and GCB lymphomas harboring these genetic lesions are called “double hit” lymphoma (c-MYC plus BCL2 or BCL6) or triple hit lymphoma (c-MYC plus BCL2 plus BCL6), respectively." (PMID 37566004, 2023). "However, mouse models that accurately mimic aggressive lymphomas, such as double hit lymphoma (DHL), an aggressive subset (~10%) of diffuse large B cell lymphomas (DLBCLs) that express high levels of both c-MYC and BCL-2 due to chromosomal translocations, are lacking." (PMID 35961968, 2022). "Interestingly, the enforced expression of BCL-2 in these lymphoma cells did not sensitise them to the BCL-2 inhibitor venetoclax, likely because these tumour cells did not develop under conditions of high BCL-2 expression and therefore do not depend on BCL-2 expression for continued survival." (PMID 35961968, 2022). "However, these prognostic indices do not capture lymphoma related molecular aberrations causing particularly aggressive high-risk disease, such as cell of origin, activated B-cell type DLBCL, MYC and/or BCL2 and/or BCL6 gene re-arranged or double expressor lymphomas." (PMID 35238275, 2022). "Although urinary Bcl-2 looks promising with an AUC of 0.90 reported in the validation cohort, this biomarker is not specific to ovarian cancer as it is also over-expressed in lymphoma, colorectal and lung cancer, and is therefore unlikely to be useful in clinical practice." (PMID 35166350, 2022). "Moreover, while BCL2 transgenic mice only develop tumors with a low frequency or after cooperation with other oncogenes (e.g., MYC), MCL1 transgenic mice were shown to develop lymphomas (predominantly FL and DLBCL) with high probability (>80%), although with a long latency (over 6 months)." (PMID 34576319, 2021).